ALB (albumin)
Diseases named in the same sentence as ALB in open-access papers (continued):
Sharing a sentence is not in itself a finding about the gene and the disease.
chronic kidney disease (continued). "The metformin-induced spurious decrease in creatinine levels may particularly affect urinary albumin measurements, which are critical for the early detection and monitoring of chronic kidney disease and diabetic nephropathy." (PMID 41019291, 2025). "This discrepancy may be attributable to the profound differences in the underlying metabolic and inflammatory states between the general population and patients with end-stage renal disease, where the drivers of albumin concentration are highly complex." (PMID 41293740, 2025). "Most patients had chronic kidney disease stage 2 to 4 with slightly low albumin levels." (PMID 41272562, 2025). "Urinary creatinine–albumin ratios, quantified by mass spectrometry (MS), guide the staging of chronic kidney disease, while serum lactate, also routinely measured by MS, serves as a prognostic marker in sepsis and traumatic shock, reflecting hypoxia and mitochondrial dysfunction." (PMID 40725110, 2025). "This study investigated the association between the C-reactive protein-albumin-lymphocyte (CALLY) index and all-cause mortality and cardiovascular disease (CVD) mortality in patients with chronic kidney disease(CKD) while exploring biological aging as a potential mediator." (PMID 41254862, 2025). "However, quality of life in end-stage renal disease patients remains substantially lower compared to the general population, with older age, high comorbidity, and low serum albumin levels identified as key contributors to poorer outcomes." (PMID 39860382, 2025). "Persistent urinary albumin excretion may lead to recurrent tubular damage and progression to chronic kidney disease." (PMID 39857389, 2025). "Additionally, chronic kidney disease (CKD) is primarily characterized by increased urinary albumin excretion and decreased glomerular filtration rate." (PMID 40535386, 2025). "Furthermore, patients that have chronic renal failure demonstrate increased carbonylation of urinary albumin by 71% compared to plasma albumin indicating the extensive damage caused by protein carbonyls." (PMID 38580664, 2024). "Chronic kidney disease (CKD)—defined as abnormalities of kidney structure or function (glomerular filtration rate [GFR] < 60 mL/min/1.73 m2 or urine albumin-to-creatinine ratio [uACR] ≥ 30 mg/g) present for at least 3 months—is an underdiagnosed public health crisis." (PMID 38592013, 2024). "Low serum albumin is often seen in nephrotic syndrome and malnourished chronic kidney disease." (PMID 39262164, 2024). "Urine albumin may be measured in 24 h urine collections or early-morning or random specimens as an albumin/creatinine ratio, with the presence of albuminuria for three or more months being indicative of chronic kidney disease." (PMID 39199326, 2024). "The blood urea nitrogen-to-albumin ratio (BAR) is used to assess renal function in chronic kidney disease patients, and the albumin-bilirubin (ALBI) score, a recently developed highly responsive model for predicting end-stage liver disease, is another practical instance." (PMID 39130833, 2024). "Moreover, the observed positive correlation between oxidized albumin and other conventional biomarkers indicates the potential utility of oxidized albumin as a metric for assessing oxidative stress in chronic kidney disease." (PMID 38395806, 2024). "Deceased COVID-19 patients were older and presented more frequently with cardiac complications, chronic kidney disease, and active malignancy, as well as higher levels of inflammatory markers, serum creatinine, and lower albumin compared to surviving patients (all p < 0.05)." (PMID 37755581, 2024). "Notably, in patients with pre-existing chronic kidney disease (CKD), albumin use was associated with worse outcomes, increasing the likelihood of 28-day mortality (p < 0.05)." (PMID 39434907, 2024).
chronic kidney disease (continued). "The identified factors associated with frailty were age, increased albumin-to-creatinine ratio (ACR), chronic kidney diseases (CKDs), and ischemic heart diseases (beta = 0.27, p = 0.003; beta = 0.24, p = 0.004; beta = 0.2, p = 0.039; and beta = 0.18, p = 0.041, respectively)." (PMID 39411191, 2024). "While, albumin/creatinine ratio (ACR) was only associated with Digit Symbol Substitution score (DSS) not Animal Fluency score (AFS), and estimated glomerular filtration rate (eGFR) was only associated with CI (AFS and DSS) at the end-stage renal disease." (PMID 37900140, 2023). "Neither an ACE inhibitor nor an angiotensin receptor blocker is recommended for the primary prevention of chronic kidney disease in diabetics with normal blood pressure, urine albumin-to-creatinine ratio (< 30 mg/g creatinine), and normal estimated glomerular filtration rate." (PMID 38012781, 2023). "Several studies indicated the positive association of a raised serum urea-to-albumin ratio with increased mortality in critically ill patients without chronic kidney diseases, septic shock or community-acquired pneumonia." (PMID 37240644, 2023). "Moreover, the Cox regression analysis showed that the increased serum albumin was an independent protective factor for the poor outcomes (eGFR decreased from the baseline ≥ 30% continuously or reached end-stage renal disease [ESRD])." (PMID 37850851, 2023). "At week 4, a significant decline in SBP was observed for older patients (aged ≥ 75 years), patients with macro-albuminuria (urine albumin-creatinine ratio > 300 mg/g), and those with chronic kidney disease stage 3–4 (estimated glomerular filtration rate [eGFR] 15 to < 60 mL/min per 1·73 m2)." (PMID 37566184, 2023). "Advanced age (p < 0.001), sex (p < 0.001), tumor stage (p < 0.001), CA19-9 (p < 0.001), albumin (p < 0.001), and chronic kidney disease stage 2 (GFR < 90 mL/min/1.37 m2; p = 0.042) were identified as independent prognostic markers for survival in a multivariate analysis." (PMID 37297851, 2023). "Firstly, centenarians may be exposed to more factors affecting albumin levels, such as disability and chronic kidney disease." (PMID 37957767, 2023). "Low baseline albumin may be due to reasons, such as long-term strict protein restriction and decreased appetite in chronic renal failure." (PMID 36762995, 2023). "Participants answered a comprehensive health questionnaire supplemented by measurements of estimated glomerular filtration rate (eGFR), urine albumin‐to‐creatinine ratio, and blood pressure and were categorized according to the chronic kidney disease classification." (PMID 35841204, 2023). "Chronic kidney disease, cardiovascular disease, increased serum creatinine (Scr), red blood cell count (RBC), platelets (PLT), apolipoprotein B (APOB), and decreased urine albumin to creatinine ratio (UACR) were significantly associated with lower VD and PD (all p < 0.013)." (PMID 36993806, 2023). "A study conducted a meta-analysis and found that UA-lowering therapy might improve the eGFR and decrease the urinary albumin/creatinine ratio in patients with chronic kidney disease." (PMID 37848834, 2023). "In male patients (76.2%), ischemic heart disease, chronic kidney disease, and cerebrovascular disease, low lymphocyte count, low albumin, high LDH, high ferritin, high C-reactive protein (CRP), high procalcitonin, and high D-dimer were considered as the high-risk factors for critical illness." (PMID 35685537, 2022). "Chronic kidney disease, another leading public health problem affecting nearly 10% of the Chinese population, is defined by estimated glomerular filtration rate (eGFR) and urine albumin-to-creatinine ratio (UACR)." (PMID 36420005, 2022). "Glycated albumin has been suggested to be an alternative to HbA1C in situations when HbA1C is not recommended for plasma glucose monitoring, such as hemoglobinopathies, pregnancy, or chronic kidney disease." (PMID 35328045, 2022).
chronic kidney disease (continued). "Alterations to albumin such as glycation, carbamylation, and bound ligands affect the renal handling of filtered albumin and likely play a role in PT toxicity and progressive chronic kidney disease." (PMID 35378997, 2022). "In addition, there are other specific comorbidities in CKD such as left ventricular hypertrophy, low serum albumin levels, elevated serum phosphate and hemoglobin levels below the international goals for chronic kidney disease." (PMID 35897379, 2022). "Protein results (albumin, prealbumin, total protein, hemoglobin, etc.)were associated with prebiotics/probiotics/synbiotics but not in adult chronic kidney disease." (PMID 36145102, 2022). "AKI has been recognized as a crucial risk factor for the occurrence and progression of CKD, which involves the gradual loss of kidney function with reduced glomerular filtration rate and enhanced urinary albumin excretion, resulting in end-stage renal disease (ESRD)." (PMID 35910356, 2022). "Lower albumin correlates with fatigue in patients with chronic kidney disease." (PMID 33283399, 2021). "Modern research shows that uremic clearance granule has the effects that reduce SCr, BUN, improve plasma albumin, improve renal anemia, calcium and phosphorus, etc., effectively delay the progress of chronic renal failure, greatly improve the life quality of patients." (PMID 34160430, 2021). "Moreover, it has been suggested that albumin oxidation occurs at early stages of chronic kidney disease, accelerating the patient requirements for dialytic treatment during disease progression." (PMID 33800425, 2021). "Thus, an increase of the COP of oxidized albumin was shown in in vitro experiments using hypochlorite, and it was also found in patients with chronic kidney disease." (PMID 34638659, 2021). "Although dietary protein restriction is recommended in cases of chronic kidney disease, our findings indicate that the dietary casein, egg albumin, and branched-chain amino acid effects might be reconsidered in the era of a phosphate-enriched diet." (PMID 33149246, 2020). "Chronic kidney disease is a common disease in dogs, and factors such as serum concentrations of creatinine, albumin, and phosphorus at the moment of diagnosis may influence the survival of these patients." (PMID 32603378, 2020). "DN is defined as increased urinary albumin excretion without any other identifiable renal diseases other than diabetes and is a leading cause of end-stage renal disease." (PMID 32397261, 2020). "Low albumin predicts mortality in patients with chronic kidney disease." (PMID 32776978, 2020). "Interestingly, in patients with chronic renal failure, carbonylation of urinary proteins and specifically albumin was 99% and 71% higher, respectively, compared with plasma." (PMID 33031394, 2020). "Chronic kidney disease (CKD) is condition characterized by a gradual and progressive loss of kidney function over time, and is defined as a reduced glomerular filtration rate (GFR), increased urinary albumin excretion, or both, present for over 3 months." (PMID 31491037, 2019). "Additionally, depression has been positively correlated with undernourishment and poorer levels of hemoglobin, ferritin and albumin, in some end-stage renal disease studies." (PMID 31314874, 2019). "Urine albumin i.e., microalbuminuria is strong indicator of chronic kidney disease." (PMID 31726798, 2019). "Low albumin has been shown to increase mortality in chronic kidney disease patients." (PMID 29853800, 2018). "There is an ongoing debate on lowering the cut-off value for albuminuria; evidence exists that the urine albumin/creatinine ratio exceeding 15 mg/g should be used to define chronic kidney disease as it better predicts kidney disease-related cardiovascular complications." (PMID 30158836, 2018).
chronic kidney disease (continued). "In addition, it was recently demonstrated that NAC reduced plasma TBARS, total AGE and pentosidine and diminished the deleterious effects of serum AGE-albumin, isolated from chronic kidney disease rats in macrophage endoplasmic reticulum stress." (PMID 29018354, 2017). "Therefore, emphasis should be placed on reducing glomerular leakage of albumin and albumin uptake by proximal TECs from the tubular lumen in chronic kidney disease." (PMID 28805677, 2017). "However, IS cannot be efficiently removed by conventional hemodialysis because of its high binding affinity to albumin in advanced chronic kidney disease (CKD)." (PMID 27843201, 2016). "Plasma levels of interleukin (IL)-1β, IL-1 receptor antagonist (IL-1RA), IL-6, tumor necrosis factor (TNF)-α, transforming growth factor (TGF)-β, high-sensitivity C-Reactive protein (hs-CRP), fibrinogen and serum albumin were measured in 3,939 Chronic Renal Insufficiency Cohort study participants." (PMID 25909952, 2015). "Serum albumin is still the most common nutritional marker used in end stage renal disease patients." (PMID 26491522, 2015). "An ADR risk score included age 65 years or more, female sex, conservatively managed end-stage renal disease, vascular disease, serum level of C-reactive protein more than 10 mg/L, serum level of albumin less than 3.5 g/dL, and the use of 8 medications or more during hospitalization." (PMID 24755778, 2014). "It has been also demonstrated, in line with increased albuminuria following high salt intake, that the activation of inflammatory processes can occur by increase of salt intake and that both the increase of the urinary level of albumin and increased inflammation can trigger end-stage renal disease." (PMID 24171109, 2013). "Interventional studies have emphasized the beneficial effects of angiotensin 2 blockers (ACE inhibitors and angiotensin receptor blockers) in reducing systemic and glomerular pressure and urinary albumin excretion and demonstrated their ability to delay end stage renal disease (ESRD)." (PMID 24349134, 2013). "In sixty-three healthy subjects and fifty-four micro-inflamed end stage renal disease (ESRD) patients circulating levels of albumin were measured by nephelometry; all subjects were also evaluated for body composition, calculated from bioelectrical measurements and an thropometric data." (PMID 22675238, 2012). "Subjects with insulin resistance may increase urinary albumin excretion, leading progressively to chronic kidney disease." (PMID 23251329, 2012). "Older individuals have been found to have glomerulopathy, that manifests as microalbuminuria (MiA, defined as urine albumin of 30–300 mg/g urine creatinine), macroalbuminuria (MaA, defined as urine albumin >300 mg/g urine creatinine), or end-stage renal disease (ESRD)." (PMID 22924029, 2012). "Several other factors were also associated with VRE acquisition in bivariate testing, including end-stage renal disease, wounds, rashes, low albumin, elevated creatinine, colonization pressure and macrolide, aminoglycoside, third-generation cephalosporin and carbapenem utilization." (PMID 21914221, 2011). "Consequently, international guidelines recommend the use of SGLT2 inhibitors in individuals with type 2 diabetes, an eGFR ≥20 ml/min per 1.73 m2 and chronic kidney disease (CKD): i.e. a reduced eGFR (<60 ml/min per 1.73 m2) or albuminuria (urinary albumin/creatinine ratio [uACR] ≥3 mg/mmol)." (PMID 41206830, 2026). "Chronic kidney disease (CKD) defined as proteinuria (urinary albumin to creatinine ratio [UACR] ≥ 30 mg /g/d) or glomerular filtration rate (GFR) less than 60 ml /min/1.73 m2 for at least 3 months." (PMID 41171478, 2025). "Recent U.S. models estimate that from 2020 to 2025, routine albumin-to-creatinine ratio testing combined with targeted nutritional interventions could prevent chronic kidney disease progression in about 1.3 million patients, reducing medical costs by roughly $16 billion." (PMID 41383296, 2025).
chronic kidney disease (continued). "Chronic kidney disease (CKD) is characterized by the presence of an estimated glomerular filtration rate (e GFR) < 60 mL/min/1.73 m2 of body-surface area or a urinary albumin excretion of >30 mg/24 hr or both for more than three months." (PMID 41327106, 2025). "Endothelin 1 also correlated negatively with total protein and albumin levels at many different time points during the follow-up period in the chronic kidney disease cohort, suggesting that it could be a predictor of total protein and albumin levels in this group of patients." (PMID 41517469, 2025). "The Albumin-Creatinine Ratio (ACR) is a key biomarker for early kidney disease detection and is predictive of chronic kidney disease (CKD) progression and associated cardiovascular risks." (PMID 40225342, 2025). "Chronic kidney disease (CKD) was defined as estimated glomerular filtration rate of <60 mL/min/1.73 m2 or albumin-to-creatinine ratio of >3 mg/mmol." (PMID 40290568, 2025). "Among comorbidities, chronic kidney disease (CKD) stage 3 to 5, cancer and lower serum albumin levels were significant predictors." (PMID 41331911, 2025). "This may be related to the fact that the majority of our patients had respiratory problems, and to the exclusion of patients with diseases that would affect their basal metabolic status and also albumin and lactate levels, such as chronic kidney disease and chronic liver disease." (PMID 40868186, 2025). "Chronic kidney disease (CKD) is identified by kidney damage (urinary albumin excretion rate ≥30 mg d−1 or equivalent) or decreased kidney function (eGFR <60 mL/min/1.73 m2) for 3 months or more." (PMID 40949128, 2025). "In addition, disease-related substances may accumulate in the organism, such as uremic toxins in chronic kidney disease, and bind to albumin with high affinity, reducing its interaction with other ligands." (PMID 41321387, 2025). "According to KDIGO, Chronic kidney disease (CKD) was defined by persistently reduced eGFR below 60 mL/min/1.73 m2, or persistent albuminuria [albumin–creatinine ratio {ACR} ≥ 30 mg/g {≥ 3 mg/mmol}], or both." (PMID 38289546, 2024). "Fourthly, the examination of underlying diseases that might influence serum ALB levels, such as liver cirrhosis and chronic renal failure, was not conducted." (PMID 38910183, 2024). "Albuminuria, characterized by an excessive amount of albumin in the urine, can occur when kidneys are damaged and is indicative of kidney diseases such as chronic kidney disease (CKD)." (PMID 38451930, 2024). "However, albumin therapy may increase 28-day mortality in certain subgroups, including patients with chronic kidney disease and baseline albumin levels >3.3 g/dL." (PMID 39434907, 2024). "A decrease in glomerular filtration rate and rise in urine albumin excretion are signs of chronic kidney disease (CKD), which affects over 10% of adult members of the general population, according to a number of community-based studies." (PMID 39415151, 2024). "In addition, hyperthyroidism, chronic kidney disease, and liver dysfunction may affect serum prealbumin and albumin levels." (PMID 39519547, 2024). "Chronic kidney disease (CKD) is defined as a reduced glomerular filtration rate (eGFR), increased urinary albumin excretion, or both, and is an increasing public health issue." (PMID 37629226, 2023). "Chronic kidney disease (CKD) severity is determined by levels of both estimated glomerular filtration rate (eGFR) and the urine albumin to creatinine ratio (ACR)." (PMID 37605228, 2023). "It was noted that blood pressure and urinary albumin were drastically reduced in chronic kidney disease (CKD) rat models treated with A. membranaceous compared to CKD rats that were untreated." (PMID 38138535, 2023).